DDX27 (DEAD-box helicase 27)
Diseases named in the same sentence as DDX27 in open-access papers (continued):
Sharing a sentence is not in itself a finding about the gene and the disease.
cancer (12 papers, 2018 to 2026). A tumor composed of atypical neoplastic, often pleomorphic cells that invade other tissues. "To investigate the effect of miR-617-mediated upregulation of DDX27 on cancer hallmarks, we co-transfected the same set of constructs in SCC131 and SCC084 cells." (PMID 38939334, 2024). "Since DDX27 is a known oncogene in other cancers, we chose to investigate it as a potential gene target for miR-617." (PMID 38939334, 2024). "Ki-67 is a representative marker of cancer malignancy, and the paired clinical specimens were utilized to observe the expression of DDX27 and Ki67 with IHC analysis." (PMID 35601484, 2022). "Nevertheless, the role of DDX27 in malignant tumors still remains largely unclear, especially in the GC metastatic process." (PMID 35601484, 2022). "In conclusion, DDX27 was significantly high-expressed in cancer contrasted to the normal breast tissue." (PMID 34362383, 2021). "miR-617-mediated upregulation of DDX27 showed a similar effect on cancer hallmarks in SCC084 cells." (PMID 38939334, 2024). "Anti-cancer effect of circUHRF2 silencing was counteracted by DDX27 overexpression." (PMID 37370759, 2023). "Large amounts of studies have regarded DDX27 as vital cancer-promoting genes in distinct tumors." (PMID 35601484, 2022). "In addition, activation of an epithelial-mesenchymal transition (EMT) has been linked to the formation of neoplastic stem cells, and DDX27 has been noticed to also regulate the cancer stem cell (CSC) activity in CRC." (PMID 35601484, 2022). "Additionally, DDX27, MDM2, RNF40, MMS22L, CCNK and LRP1B were detected as missense mutational cancer gene." (PMID 34313788, 2021). "DDX27 was also related to the development of malignant tumor." (PMID 34362383, 2021). "We next assessed DDX27 expression among various human cancers." (PMID 29535419, 2018). "Next, to explore the potential molecular effectors of the miR-617/DDX27 axis, we chose to examine the PI3K/AKT/MTOR pathway as it is one of the most frequently activated pathways in cancers, including OSCC." (PMID 38939334, 2024). "miR-617-mediated upregulation of DDX27 is a novel mechanism in OSCC and underscores the therapeutic potential of synthetic miR-617 mimics in cancer therapeutics." (PMID 38939334, 2024). "This suggested that DDX27 acts as a negative regulator of cell viability and proliferation in OSCC cells contrary to its oncogenic role in other cancers." (PMID 38939334, 2024). "Some of them are only overexpressed across human cancers, such as DDX27, DDX41 and DDX56, while most of them are both overexpressed and lost in different cancer types." (PMID 36761420, 2022). "By calculating the proportion of immuno-staining with high, medium, low, or not detected in different cancer types as reported by HPA, we found DDX27 and PLOD2 showing medium to high tumor-specific staining in multiple cancer types." (PMID 33287876, 2020). "We also observed the overexpressed mRNA level of DDX27 and PLOD2 in various cancer types in Gene Expression Profiling Interactive Analysis (GEPIA)." (PMID 33287876, 2020). "Up-regulation of DEAD-box helicase 27 (DDX27), a member of DEAD-box RNA helicase superfamily, was found in most cancer types." (PMID 33287876, 2020). "Contrary to its oncogenic role in other cancers, cell viability and proliferation assay in OSCC cells surprisingly showed a reduction in total viable cell count and proliferation upon DDX27 overexpression, thereby suggesting an anti-proliferative role of DDX27 for the first time in OSCC cells." (PMID 38939334, 2024). "On the other hand, DDX27, RNF40, MMS22L and CCNK have not been reported as mutational cancer genes in previous studies." (PMID 34313788, 2021). "Analysis based on TCGA-BRCA database showed that DDX27 was significantly high expressed in cancer whether it's a paired analysis or not (p < 0.0001)." (PMID 34362383, 2021).
tumor (10 papers, 2018 to 2025). "Analysis based on DDX27 expression and clinicopathological factors proved that high expression of DDX27 was closely associated with larger tumor size, positive lymph nodes, higher ki-67, higher histological grade and later TNM stage." (PMID 34362383, 2021). "According to our research, the expression level of DDX27 had a closely association with larger tumor, positive lymph nodes, higher histological grade, later TNM stage and a worse prognosis." (PMID 34362383, 2021). "In these patient samples, DDX27 levels were either downregulated, upregulated, or unchanged in the tumor tissues compared to the paired normal oral tissue samples." (PMID 38939334, 2024). "Collectively, these findings suggest that circ_RNF13 and DDX27 were upregulated in CRC tumor samples and cells." (PMID 36551703, 2022). "In this study, we demonstrated that circ_RNF13 and DDX27 were upregulated in CRC tumor samples and cells." (PMID 36551703, 2022). "To unveil the role of DDX27 in tumor malignancy, we successfully constructed a stable DDX27 overexpression (LV-DDX27) and knockdown (shDDX27) cell models in three GC cell lines (AGS, HGC-27, and BGC823) using recombinant lentivirus infection." (PMID 35601484, 2022). "High expression of DDX27 was related to larger tumor size (p = 0.0005), positive lymph nodes (p = 0.0008), higher histological grade (p = 0.0040), higher ki-67 (p = 0.0063) and later TNM stage (p < 0.0001)." (PMID 34362383, 2021). "DDX27 expression (p = 0.0289), tumor size (p = 0.0004), lymph node status (p < 0.0001) and TNM stage (p = 0.0001) were correlated to worse DFS in univariate analysis." (PMID 34362383, 2021). "Conversely, silencing of DDX27 exerted opposite effects in vitro and significantly inhibited murine xenograft tumor growth and lung metastasis in vivo." (PMID 29535419, 2018). "Similarly, our data illustrated that DDX27 was markedly elevated in CRC tumor samples and cells which was in accordance with previous reports." (PMID 36551703, 2022). "The positive correlation between TRIM24 and DDX27 was also found in collected CRC tumor samples." (PMID 36551703, 2022). "TCGA data revealed that DDX27 was upregulated by 2.33-folds in CRC tumor samples." (PMID 36551703, 2022). "Results: circ_RNF13 and DDX27 were elevated in CRC tumor samples and cells." (PMID 36551703, 2022). "Silencing NPM1 abrogated DDX27-activating NF-κB signaling and its tumor-promoting function." (PMID 29535419, 2018). "Ectopic expression of DDX27 significantly accelerated tumor growth in nude mice (P < 0.01)." (PMID 29535419, 2018). "We stratified the cohort according to tumor site and DDX27 expression." (PMID 29535419, 2018). "Hence, DDX27- NPM1-NF-κB forms a functional axis that cooperatively regulates tumor progression." (PMID 29535419, 2018). "In this connection, DDX27 may promote tumor survival and EMT via activation of NF-κB." (PMID 29535419, 2018). "To study the roles of circ_RNF13 and DDX27 in CRC, we first examined their expression in CRC tumor samples." (PMID 36551703, 2022). "Interestingly, TCGA data showed that TRIM24 was upregulated by 1.75-fold in CRC tumor samples, and there was a positive correlation between TRIM24 and DDX27 in CRC tumor samples." (PMID 36551703, 2022). "Current studies demonstrate that both DDX27 and LPP are involved in the tumor EMT process." (PMID 35601484, 2022). "More importantly, DDX27 is highly amplified and overexpressed in CRC tumor samples." (PMID 36551703, 2022). "In Beijing cohort, DDX27 expression was independent of age, sex and TNM classification, but was found to be associated with tumor site (colon or rectum)." (PMID 29535419, 2018). "Knockdown of NPM1 abrogated the tumor-promoting function of DDX27, as indicated by MTT assays, without affecting DDX27 expression." (PMID 29535419, 2018).
infection (2 papers, 2022 to 2025). The state of being infected such as from the introduction of a foreign agent such as serum, vaccine, antigenic substance or organism. "GP2a is a key structural protein involved in viral assembly and infection, and its degradation by DDX27 represents a novel antiviral strategy." (PMID 40574840, 2025).
colorectal (1 paper, 2018). "DDX27 is a novel oncogene involved in colorectal carcinogenesis through increasing cell proliferation, inhibiting apoptosis and promoting metastasis." (PMID 29535419, 2018). "Collectively, these results indicate that DDX27 exerts oncogenic properties in colorectal carcinogenesis via promoting cell proliferation, inhibiting apoptosis and increasing metastatic abilities." (PMID 29535419, 2018).
gastrointestinal tumors (1 paper, 2022). "TCGA gene expression profiling showed that the high expression of DDX27 was exhibited in the gastrointestinal tumor tissues, especially in stomach adenocarcinoma (STAD)." (PMID 35601484, 2022). "Therefore, we first assessed the DDX27 expression among various gastrointestinal tumors." (PMID 35601484, 2022).
DDX27 also shares sentences with these, for which no sentence is quoted: cervical cancer (1 paper); colorectal tumor (1); endometrial tumors (1); gastrointestinal disease (1); lipoma (1); liver cancer (1); renal carcinoma (1); uterine cancer (1).